INS (insulin)
Diseases named in the same sentence as INS in open-access papers (continued):
Sharing a sentence is not in itself a finding about the gene and the disease.
diabetes (continued). "This scale is important for identifying insulin treatment self-management skills as well as nursing care and self-management needs and to attain a desired level by the diabetes nurses." (PMID 30905141, 2019). "PTP1B is a negative regulator of the insulin signalling pathway and considered a potential target to treat diabetes." (PMID 31083362, 2019). "The conclusions from the recent studies on variability of postprandial glucose response, if confirmed in people with diabetes, should result in more personalized algorithms for prandial insulin dose calculation in the future." (PMID 30871141, 2019). "To date, the available therapy for diabetes includes insulin and various oral antidiabetic agents such as sulfonylureas, thiazolidinediones, and α-glucosidase inhibitors." (PMID 31178917, 2019). "Treatment with glargine-based basal insulin therapy in diabetes with Stage 3 or Stage 4 CKD was efficacious in reducing glycemic parameters and was safe without significant changes in weight and hypoglycemia." (PMID 31890395, 2019). "Children with Type 1 diabetes were significantly more likely to be insulin‐treated at the time of diabetes diagnosis and at the time of recruitment into the study." (PMID 31276222, 2019). "He had been treated with insulin therapy, water and salt replacement according to the International Society of Pediatric and Adolescent Diabetes guidelines for management of diabetic ketoacidosis (DKA) for 48 h." (PMID 30616577, 2019). "Diabetes mellitus (DM) is a metabolic disorder in which there is an aberration in the secretion and/or action of insulin." (PMID 31700753, 2019). "Diabetes manifests when β cells cannot compensate for the increasing demand in insulin to maintain euglycemia." (PMID 29957055, 2019). "The fixed 4-h re-activation of insulin delivery was introduced to prevent the occurrence of diabetes ketoacidosis." (PMID 30922295, 2019). "It is well-established that hypertensive patients have whole body metabolic complications such as hyperlipidemia, hyperglycemia, decreased insulin sensitivity or diabetes mellitus." (PMID 31040794, 2019). "The specific PPARγ ligands the thiazolidinediones (TZDs) improve clinical insulin sensitivity in type 2 diabetes mellitus." (PMID 31068841, 2019). "Type 2 diabetes mellitus is a chronic medical condition characterised by inadequate insulin production and action resulting in hyperglycaemia." (PMID 31303866, 2019). "Diabetes is defined as a group of metabolic diseases characterized by hyperglycemia resulting from defects in insulin secretion, insulin action, or both." (PMID 30700010, 2019). "Type 2 diabetes mellitus is a kind of chronic disease characterized by obesity, hyperglycemia, impaired insulin secretion, and insulin resistance." (PMID 31093312, 2019). "There was a significant burden of comorbidities in this population including 100% with diabetes including 40% on insulin, 91.4% with hypertension, 48.6% with current or former tobacco use." (PMID 31174526, 2019). "Insulin (INS) as the most widely used hypoglycemic agent was always chosen as the most effective treatment method of diabetes." (PMID 31257946, 2019). "The aim of this study was to investigate the effect of diabetes mellitus treated with insulin and oral antidiabetic drugs on clinical outcomes after TAVI." (PMID 31138207, 2019). "Insufficient secretion or hypoactivity of insulin can lead to diabetes mellitus; a metabolic disorder characterised by persistent hyperglycaemia." (PMID 31829209, 2019). "Insulin treatment, healthy eating appropriate for the diabetic state and physical activity are important in diabetes management." (PMID 30015620, 2019). "Only two (5%) GPs changed their patient’s diabetes treatment as a result of the diagnosis of cognitive impairment (one increased the HbA1c target, one lowered the insulin dosage)." (PMID 30833988, 2019).
diabetes (continued). "Pioglitazone treatment for 16-weeks increased adiponectin levels in an obese population of Chinese subjects with diabetes and this correlated with improved insulin secretion and insulin sensitivity." (PMID 31920962, 2019). "A total of 2653 (31%) patients had diabetes at baseline, of which 979 (37%) patients were treated with insulin." (PMID 31271255, 2019). "Proportion of patients continuing non-insulin diabetes medications after insulin initiation comparing baseline monotherapy versus combination therapy users." (PMID 30759121, 2019). "The efficacy and safety of insulin glargine, a long-acting insulin analog, is well-established in both type 1 diabetes mellitus (T1DM) and T2DM." (PMID 31890395, 2019). "A potential therapeutic strategy for diabetes is the transplantation of induced-insulin secreting cells." (PMID 30191384, 2019). "The correlation analysis indicated that the PD-1 on NK cells has a positive correlation with insulin and diabetes duration." (PMID 31008114, 2019). "In diabetes, accumulation of ketone bodies occurs due to the effects of insulin resistance and increased dependence on fats as fuels." (PMID 31336875, 2019). "Both use of insulin or combination of insulin and oral medication were found to be significant predictors of participants’ rating of the overall severity of their diabetes." (PMID 31796044, 2019). "The frequency of severe hypoglycemia requiring emergency services in patients receiving insulin therapy depends on how diabetes is managed for type 1 and type II DM." (PMID 31652253, 2019). "The concentrations of GHbA1c, insulin, and pyruvate kinase are correlated with glucose levels and therefore are viewed as dependable indexes for the diagnosis of diabetes." (PMID 30881587, 2019). "Hypoglycemia incidence among patients with insulin-treated diabetes was assessed across 26 sites in Colombia." (PMID 31584770, 2019). "Our multivariate analyse revealed that diabetes status (p = 0.893; OR 0.95, 95% CI 0.48–1.91) and then insulin (p = 0.380; OR 0.71, 95% CI 0.33–1.52) added little if any independent information on non-completion and were removed from further consideration." (PMID 31651309, 2019). "Although high acute FFA concentrations in β-cells have been shown to promote β-cell proliferation, the chronic lipotoxic condition occurring in diabetes can promote the impairment of insulin secretion and eventually induce β-cell death." (PMID 31487953, 2019). "Insulin signaling governs many processes including glucose homeostasis and metabolism, and is therapeutically used to treat hyperglycemia in diabetes." (PMID 31740700, 2019). "Overall, a higher proportion of patients on combination medications continued the diabetes medications than patients that had been on non-insulin monotherapy at baseline (88.6% versus 80.0%, respectively)." (PMID 30759121, 2019). "Eighty‐five percent of the responders reported spending less time managing their child's diabetes (finger‐pricks, insulin therapy adjustment, regular data review) with closed‐loop." (PMID 31140654, 2019). "A previous cross-sectional study described self-administration techniques for insulin in patients with diabetes mellitus; these authors reported that 88.8% of participants used water and soap or liquid detergent before preparing and administering the insulin." (PMID 30974788, 2019). "For type 1 diabetes mellitus, resulting from selective destruction of insulin producing cells by exaggerated immune reaction, the only effective therapy remains exogenous insulin administration." (PMID 30804929, 2019). "Diabetes-specific nutritional regimens that reduced glycemic excursions, as well as algorithm-driven insulin delivery approaches that allowed for flexible glucose-responsive insulin dosing, were both effective in improving glycemic control." (PMID 31261760, 2019). "FGF19 also stimulates glycogen synthesis in mice with streptozotocin-induced diabetes with very low insulin levels." (PMID 30927227, 2019).
diabetes (continued). "The patients' history of diabetes-related morbidities recording the patient’s intake of insulin was also recorded." (PMID 31903311, 2019). "Diabetes is a metabolic disease characterized by marked hyperglycemia due to defects in insulin secretion and/or insulin action, as well as polyphagia and blurred vision." (PMID 31835423, 2019). "Regardless of removal mechanism, our data should be interpreted in the context of current recommendations for the administration of insulin to patients with diabetes who require dialysis." (PMID 31015539, 2019). "The HbA1c is a simple and reliable marker used to accurately estimate insulin sensitivity in persons with diabetes." (PMID 31075962, 2019). "The few core keywords used were: micro-RNA, diabetes, obesity, inflammation, pancreas, adipose tissue, insulin, leptin, adipogenesis, metabolic syndrome." (PMID 31404962, 2019). "Strong predictors of depression in patients with diabetes include female gender, longer duration of diabetes, non-insulin treatment, and complications including neuropathy, nephropathy, and foot ulcers." (PMID 31131177, 2019). "Oxidative stress impairs β-cell function, which reduces the production of insulin by impairing glucose-stimulated insulin secretion, thereby creating a state of hyperglycaemia, which ultimately leads to the development of diabetes mellitus." (PMID 31745461, 2019). "At present, the first choice for clinical treatment of diabetes is still insulin (INS), which is secreted by islet beta cells in the pancreas, the only hormone in the body to lower blood sugar." (PMID 31257946, 2019). "Polysaccharides from mycelia and hot water extracts of fruiting bodies of P. linteus were useful for diabetes treatment by reducing oxidative damage of islet cells, promoting insulin secretion, and enhancing insulin resistance." (PMID 30704063, 2019). "Additional evidence for a role of insulin in supporting cognitive functioning comes from rodent models of diabetes, in which insulin secretion is reduced." (PMID 31057368, 2019). "IR is a vital factor in the pathogenesis and etiology of type 2 diabetes mellitus, which is characterized by an impaired ability of insulin to promote glucose uptake and utilization." (PMID 31019978, 2019). "Diabetes is a chronic disease arising from impaired insulin secretion and insulin resistance, leading to its defining feature of hyperglycemia." (PMID 31137754, 2019). "It has been indicated that ginsenosides can impress insulin production/secretion, glucose metabolism/uptake, and inflammatory pathway in diabetes." (PMID 31611749, 2019). "At the moment, the only effective treatment for one of the major types of diabetes are daily insulin injections." (PMID 30747102, 2019). "It is not uncommon for PWD admitted to hospital (for diabetes or non-diabetes related reasons) to have reduced overall control of their condition, with insulin treatment, timing of meals and glucose monitoring affected." (PMID 31391081, 2019). "Excluding MSC differentiation as a mechanism for the improved healing, another possible mechanism is that the system cured the animals of diabetes by delivering insulin, and thus in that way mitigating the wound healing deficits common to diabetics." (PMID 31719928, 2019). "This physiological action of insulin is important in maintaining glycaemic control post-prandially, and indeed diabetes is diagnosed by an elevation in fasting blood glucose (or circulating glycated hemoglobin) above clinically defined thresholds." (PMID 31920989, 2019). "Preserving the capacity of beta-cells to produce insulin according to changing need is a cornerstone in the treatment of diabetes." (PMID 30813546, 2019). "Type 2 diabetes mellitus is a metabolic disorder characterized by impaired insulin action (insulin resistance), followed by compensatory mechanism of beta cells that secrete excess basal insulin (hyperinsulinemia) to maintain glucose homeostasis." (PMID 31569751, 2019).
diabetes (continued). "A previous study showed that total insulin and IGF1 resistance in pancreatic β cells causes overt diabetes." (PMID 30778335, 2019). "We conclude that prandial insulin doses in treatment of people with diabetes should take into account the pre-meal glycemia as well as the size and composition of meals." (PMID 30871141, 2019). "The most commonly prescribed antihyperglycemic agents among patients with CKD and diabetes or prediabetes were insulin (38 278 [10.0%]), metformin (30 393 [7.9%]), and sulfonylureas (16 989 [4.4%])." (PMID 31860111, 2019). "Concomitant measurements of GH (by a radio-immunoassay sensitive to 0.4 mug/ml) revealed that GH levels are similarly elevated in uncontrolled diabetes, normalizing as insulin response reduces plasma glucose and improves intracellular glucose economy." (PMID 31636602, 2019). "Data from five European countries in 2010 show that spending on diabetes medicines (insulin and oral medicines for diabetes) was between 6.2% (France and Italy) and 10.5% (Spain) of total direct cost of diabetes care." (PMID 31551632, 2019). "P. ginseng plays an important role in lowering glucose level, promoting insulin secretion, alleviating diabetes complications such as hypomagnesemia, hyperlactatemia, acid-base disturbance, and dyslipidemia." (PMID 31231500, 2019). "Total costs of treating diabetes which included costs of insulin, costs related to diabetes complications and indirect costs amounted to HKD 762,136 for a patient receiving glargine U100 and HKD 740,776 for a patient using NPH." (PMID 31303866, 2019). "Diabetes mellitus is characterized by chronic hyperglycemia resulting from flaws in insulin action, insulin secretion, or both." (PMID 31064136, 2019). "T2DM is responsible for more than 85% of total diabetics and is characterized by an impairment of pancreatic beta cells in the pancreas of patients, which compromise the capacity of the organism in using insulin." (PMID 31756981, 2019). "Only 37 (2.7% of the cohort) had an undefinable outcome due to intermediate C-peptide levels (200–600 pmol/L when insulin-treated diabetes within 3 years of diagnosis)." (PMID 31558459, 2019). "Diabetes was characterised by elevated GHb, fed/fasting blood glucose and increased fasting insulin." (PMID 31541173, 2019). "The uncontrolled hepatic glycogenolysis and gluconeogenesis and decreased utilization of glucose by the insulin dependent tissues are the fundamental factors contributing to a condition termed as hyperglycemia in diabetes mellitus." (PMID 31142215, 2019). "Although the patient had a good response to systemic steroid, he developed diabetes mellitus that was uncontrolled on oral hypoglycemics and required subcutaneous insulin therapy." (PMID 31335311, 2019). "One possible treatment for diabetes is the transplantation of glucose-responsive insulin-secreting cells into the body." (PMID 31547868, 2019). "Proper enhancement of postprandial endogenous insulin aimed at suppressing postprandial glucose output without stimulating excessive glucose uptake in the periphery is potentially useful for treating diabetes with insulin antibody-induced glycemic instability." (PMID 30621663, 2019). "Diabetes is a group of metabolic diseases characterized by chronic blood glucose elevation due to insufficient insulin secretion or reduced insulin sensitivity." (PMID 31281399, 2019). "Because in patients with type 2 diabetes insulin therapy retained the ability to lower blood glucose despite hyperinsulinemia and insulin resistance, many hoped that, despite hyperleptinemia, leptin therapy might be effective in typical obesity and obesity-associated diabetes." (PMID 30357355, 2019). "There are key public health issues with cost and access to antidiabetic medicines, especially insulin, and to specialised diabetes care." (PMID 31637025, 2019).
diabetes (continued). "Two major drugs like (i) insulin and (ii) oral hypoglycemic agents which are the first line of treatment for diabetes have some side effects and fail to significantly alter the course of diabetic complications." (PMID 31885647, 2019). "Type 2 diabetes mellitus (T2DM) is a complex metabolic disorder characterized by hyperglycemia arising from insufficient insulin secretion and insulin resistance." (PMID 30795583, 2019). "Although patients with type 1 diabetes received lower insulin doses than patients with type 2 or secondary diabetes and lower than those recommended in the UK guidelines, they had more episodes of hypoglycaemia (including profound hypoglycaemia)." (PMID 31418117, 2019). "Type 2 diabetes mellitus (T2DM) is a metabolic disorder characterized by dysfunction and progressive loss of pancreatic β-cells, which are responsible for insulin synthesis, originating tissue damage and several long-term complications." (PMID 31412623, 2019). "and third, how does the enhanced basal insulin secretion occur and what is the relevance to aging or diabetes mellitus?" (PMID 31721726, 2019). "Diabetes is a chronic disease characterized by a decreased production of insulin and by a reduced efficacy of the insulin produced." (PMID 30863457, 2019). "Due to the corticosteroids therapy, he developed diabetes mellitus, which necessitated insulin therapy." (PMID 31335311, 2019). "Diabetes mellitus, a common metabolic disorder, is characterized by hyperglycemia resulting from insulin resistance, inadequate insulin secretion, or excessive glucagon secretion." (PMID 31275749, 2019). "Insulin-dependent (type 1) and insulin-independent (type 2) diabetes are the two major variations of diabetes seen among humans." (PMID 31842333, 2019). "Diabetes mellitus is a complex metabolic disease characterized by high serum glucose concentration and insulin resistance in target tissues and/or defects in insulin secretion." (PMID 31289463, 2019). "Obesity-related and diabetes-related metabolic disorders, such as impaired insulin sensitivity and non-alcoholic fatty liver disease (NAFLD)/non-alcoholic steatohepatitis (NASH), contribute to increasing the incidence of HCC with a non-viral etiology." (PMID 30704150, 2019). "Liver is a major target of insulin action, the onset of diabetes is accompanied by development biochemical and functional abnormalities in the liver including alteration in carbohydrate, lipid, protein metabolism, and change in antioxidant status." (PMID 30805033, 2019). "Diabetes is a disease characterized by high blood sugar levels as a consequence of the body’s inability to produce and/or use insulin." (PMID 31635378, 2019). "Diabetes mellitus is a serious health condition resulting from defects of insulin secretion and/or insulin action." (PMID 31682586, 2019). "The cost-benefit principles span the key area of diabetes from the patients to analyze the record statistics of insulin level or with other treatment terminologies of diabetic patients." (PMID 31300715, 2019). "We cannot exclude the possibility that Trpc6del/del rats are at least partially insulin‐resistant by the time we started our experiments, which would negate protective effects in diabetes to a greater extent than in other disease models we have examined." (PMID 32123821, 2019). "In strong contrast, systemic inhibition of PKD using the compound CID755673 accelerated onset of diabetes in BTBRob/ob mice, as evidenced by increased fasting blood glucose and decreased insulin secretion in response to glucose injections." (PMID 31346174, 2019). "The diabetes duration was fairly short in our study participants, increasing the likelihood to observe an increase in postprandial incretin and insulin secretion." (PMID 30813546, 2019). "PTP1B has gained much attention in recent years due to its ability to attenuate insulin signaling and is currently regarded as a possible therapeutic target against metabolic syndrome, obesity and diabetes." (PMID 31319588, 2019).